TNF (tumor necrosis factor)
Diseases named in the same sentence as TNF in open-access papers (continued):
Sharing a sentence is not in itself a finding about the gene and the disease.
breast carcinoma (continued). "Inflammatory cytokines, including TNF-α, IL-6, and prostaglandin E2, may promote the development of breast cancer by promoting cell proliferation and cell cycle progression." (PMID 38273418, 2024). "Examples of these pathways include bladder cancer, endocrine resistance, GnRH signaling, estrogen signaling, ErbB signaling, colorectal cancer, PD-L1 and PD-1 checkpoints, IL-17 signaling, choline metabolism in cancer, breast cancer, TNF signaling, chemical carcinogenesis, and pathways in cancer." (PMID 39707884, 2024). "Monocytes, as a type of inflammatory cells, not only secrete inflammatory factors such as IL-1, IL-6, IL-10, and TNF-α to promote tumor microangiogenesis, but also assist in the adhesion of tumor cells to endothelial cells, thereby promoting breast cancer metastasis." (PMID 38834662, 2024). "This concept could be developed as a novel treatment for improving the outcomes for breast cancer patients by using infliximab to decrease the effects of TNF-α together with ATX-LPA inhibitors." (PMID 38201482, 2023). "Therefore, the mechanism by which TNFα promotes chemotherapeutic resistance in breast cancer should be further investigated." (PMID 37787041, 2023). "Secreted factors such as leukotriene B4 (breast cancer), glioma cell-derived placental growth factor (glioma), TNF-α (tumor cells), and IL-21 (T cells), as well as cell contact-dependent mechanisms (CD40-CD40L and PD-1-PD-L1 axis,), promote cell differentiation Bregs in the TME." (PMID 37568713, 2023). "Matrix metalloproteinase-2 activity is inhibited by DAI to produce an anticancer effect, and its non-toxic concentration is also extensively used to modulate Hedgehog signaling to prevent tumor necrosis factor-induced migration and the invasion of human breast cancer cells." (PMID 36838751, 2023). "Disturbance in the TNF signaling pathway leads to breast cancer." (PMID 37180727, 2023). "In breast cancer patients with low ferroptosis activation, TNF might be used as an antitumor treatment, but its basic mechanism needs further exploration." (PMID 37212877, 2023). "Additionally, TNFα was shown to sensitize breast cancer cells to chemotherapy, including CDDP, and subsequently enhanced the cytotoxic effect on cancer cells." (PMID 37331004, 2023). "EVs secreted by breast cancer cells have been reported to stimulate NF-κB activation in macrophages, leading to the secretion of inflammatory cytokines such as IL-6, tumor necrosis factor-alpha (TNFα), granulocyte colony-stimulating factor (GCSF), and CCL2." (PMID 38111675, 2023). "For instance, tumor necrosis factor-α (TNF-α) is a significant proinflammatory cytokine that has been found in tumor microenvironments, it is involved in all stages of breast cancer development and affects the proliferation, metastasis, and recurrence of breast cancer." (PMID 37304237, 2023). "TNF-α plays a dual role in cancer and can enhance or inhibit tumor progression depending on the discovery of its specific cellular environment.High serum TNF-α remains an independent prognostic factor for poor overall survival in a case-control study of primary breast cancer patients." (PMID 37007080, 2023). "However, serum TNF-α levels were found to be significantly elevated in higher grade breast cancers and those with lymph node metastases compared with earlier stage I cancers." (PMID 36980727, 2023). "No other studies have examined the impact of lysicamine on cell migration in cancer cell lines; however, research on apomorphine, another alkaloid, demonstrated its ability to suppress cell invasion, as well as TNF-α-induced MMP9 expression in breast cancer cells." (PMID 38139812, 2023). "Similar results were observed for TNF with the stage IV individually analyzed, presenting a greater reduction in inflammatory cytokine secretion in comparison to controls and early stages of breast cancer." (PMID 37628945, 2023).
breast carcinoma (continued). "Specifically, the study revealed that preoperative hydroxyprogesterone manifests its effect in patients with breast cancer by downregulating genes involved in inflammatory response and production of TNF that are known to induce proliferative, invasive, and malignant behavior of breast cancer cells." (PMID 37395734, 2023). "In addition, our study identified that ProLBS in combination with prebiotic FOS supplementation effected a reduction in level of circulating TNF-α [MD = −15.06; 95% CI: −23.20 to −6.91; p = 0.0003] in the population of breast cancer survivors." (PMID 36829557, 2023). "Considering our previous results showing that cats with mammary carcinoma have higher circulating levels of several immunomodulatory molecules (IL-6, TNF-α, CTLA-4, PD-1, PD-L1, VEGF-A, VEGFR-1, VEGFR-2, and LAG-3), the serum TIM-3 levels were evaluated to check for statistical correlations." (PMID 36672332, 2023). "Its expression is induced by tumor-derived TNFα in breast cancer cells." (PMID 36996146, 2023). "Macrophages secrete S1P, IL-6 and TNFα, thereby promoting breast cancer metastasis." (PMID 36670988, 2023). "Recent research has revealed that exercise may significantly exhibit decreased post-operative IGF-1, CRP, TNFα, and Il-6 levels in adult and older adult women with breast cancer." (PMID 37958310, 2023). "Variations in TNFα, PPARγ, and IRS-1 genes are associated with survival in breast cancer patients." (PMID 37886170, 2023). "The correlation analysis of TCGA-BRCA (breast cancer) revealed several inflammatory pathways associated with increased tumor NOS2/COX2 expression that influenced clinical outcomes, including the antitumor-associated IFNγ, TNFα, IL2, IL1, and IL17 pathways." (PMID 37169743, 2023). "A recent study showed that 12 weeks of yoga reduced TNF-α levels in breast cancer patients." (PMID 36751235, 2023). "Although the process of tumor cell attachment to the endothelium during metastasis is complex and multifactorial, the production of TNF-α-induced endothelial E-selectin by tumor cells appears to represent a pivotal stage in the progression of breast cancer liver metastasis." (PMID 37507468, 2023). "Concerning aerobic exercise carried out in clinical studies, although some analyses report no significant benefits related to inflammation, other research stresses that this form of training, along with diet, helps decrease TNF-α and IL-6 serum concentrations in women with breast cancer." (PMID 36612320, 2023). "As in the heatmap, the liver and kidney function, coagulation factors and routine blood test results of 84 breast cancer blood samples were retrospectively analyzed to explore the correlation between the two cytokines, IL-4 and TNF-α, the statistically significant results are marked with *." (PMID 37007080, 2023). "Moreover, M2b macrophages were able to promote breast cancer cell migration and metastasis via TNF-α, as the depletion of TNF-α in M2b culture medium reduced the migration of tumor cells in a co-culture system." (PMID 37108657, 2023). "TNFα may promote breast cancer cell stemness through the nuclear factor kappa B (NF-κB) pathway, or through inducing dedifferentiation of melanoma cells resulting in downregulation of tumour antigens thereby promoting immunoevasion." (PMID 37455828, 2023). "In breast cancer, TNFα inhibition has been shown to increase the sensitivity to doxorubicin." (PMID 36835413, 2023). "Breast cancer patients with psychological distress displayed poor cognitive function, poor memory, and inferior quality of life, which was accompanied by higher cytokine levels of IL‐1β, TNF‐α, and IL‐4." (PMID 36965094, 2023). "Thus, it was important to dissect the role of TNF-α-induced inflammation in ATX-LPA signaling in breast cancer." (PMID 38201482, 2023). "For instance, cytokines like IL-1β, IL-6, IL-8, and TNF-α play a crucial role in breast cancer." (PMID 37569777, 2023).
breast carcinoma (continued). "TNF-α could promote breast cancer stem cell (BCSC) self-renewal capacity in human breast cancer cell lines through upregulating TAZ and activating non-canonical NF-κB pathway." (PMID 37130846, 2023). "Furthermore, TNFα was found to sensitize breast cancer cells to radiotherapy and chemotherapy through DNA damage and triggering necroptosis." (PMID 37331004, 2023). "Infliximab is a monoclonal antibody against TNF-α which was used to neutralize activity by binding to soluble and transmembrane forms of TNF-α and stopping interactions with its receptors in a syngeneic model of breast cancer in BALB/c mice to understand its primary effect on tumor progression." (PMID 38201482, 2023). "Furthermore, IL‐1β, TNF‐α, and IL‐4 did mediate the relationship between psychological distress and cognitive function in breast cancer survivors." (PMID 36965094, 2023). "Indeed, miR-182 has been shown to play a role in the TGF-β-induced bone metastasis of breast cancer and TNF-α-mediated osteoclastogenesis." (PMID 37127752, 2023). "TNF-α can induce breast cancer stem cells by upregulating Slug through NF-κB/HIF1α17." (PMID 37063424, 2023). "TNFα plays a central role in initiation, promotion and metastasis of breast cancer." (PMID 36941680, 2023). "Our team has demonstrated that soluble TNFα (sTNFα) secretion by HER2+ breast cancer cells induces resistance to the anti-HER2 therapy trastuzumab, by upregulating the expression of the transmembrane glycoprotein mucin 4 (MUC4) through activation of the NF-kB pathway." (PMID 37284199, 2023). "Therefore, targeting the genes involved in the TNF signaling pathway can help block the pathogenesis of breast cancer." (PMID 37180727, 2023). "Additionally, inflammasome pathway and IL-1β production can also be elicited by ATP or TNF-α through the P2Y2 receptor (P2Y2R) in breast cancer cells, which promotes the expression of matrix metallopeptidase-9 (MMP-9) and resultant invasion." (PMID 36932407, 2023). "In addition, genome-wide transcriptional profiling has demonstrated that the combined treatment of MCF7 breast cancer-derived cells with the chemotherapeutic agent doxorubicin and the inflammatory cytokine TNF-α results in the synergistic induction of ETV7." (PMID 37041130, 2023). "This study revealed a significant association between serum PD-L1 and IFNα2 and TNFα levels in breast cancer, though not in normal controls." (PMID 35053979, 2022). "In addition, elevated serum concentrations of IL-6, IL-10, IL-1β, and TNF-α are found in a variety of cancer types, including breast cancer." (PMID 36482346, 2022). "Therefore, serum TNF-α levels are of great significance for evaluating the progression, diagnosis, and treatment of breast cancer." (PMID 35783155, 2022). "Exercise reduces the postoperative levels of IGF-1, IL-6, CRP, IL-10 and TNF-α among patients with breast cancer, which may have a significant impact on inhibiting breast cancer recurrence and improving its prognosis." (PMID 36482346, 2022). "The physiologically achievable concentration of DFO monotherapy significantly active the apoptosis of breast cancer cells and the xenotransplantation of mouse breast tumors by activating the tumor necrosis factor-α (TNF-α)/nuclear factor kappa B (NF-κB) axis and transform growth factor β (TGF-β)." (PMID 36467032, 2022). "It is also possible to speculate that TNF-α effects on the estrogen-responsive breast cancer cells through signaling pathways other than the mitochondrial respiratory supercomplex formation and metabolism." (PMID 35178385, 2022). "In preclinical models of breast cancer, TNF signaling may promote migration and invasion of breast cancer cells, as well as to induce apoptosis and exert cytotoxic effects in vitro." (PMID 35432372, 2022).
breast carcinoma (continued). "PTHrP is expressed in 60% of invasive breast tumors, suggesting that substantial proportion of hypercalcemia present in breast cancer patients with extensive bone metastasis, often recognized as LOH, is caused by multiple humoral factors including PTHrP, TNFα, and interleukins." (PMID 36435947, 2022). "Administration of oncolytic measles virus expressing secretory HP-NAP improved the survival of the mice with metastatic breast cancer and increase the level of pro-inflammatory cytokines, including IL-12/23, TNF-α, and IL-6, in pleural fluids of mice with pleural metastasis of breast cancer." (PMID 36613542, 2022). "Therefore, it is of great importance to study the relationship between inflammatory factors (IL-1β, IL-8, TNF-α) and breast cancer." (PMID 35188865, 2022). "In addition, STAT3 was reported to be activated by inflammatory cytokines, such as IL6, IL8 and TNFα, which enhance breast cancer proliferation, invasion and metastasis through the upregulation of Twist, Snail, Slug, Vimentin and HIF-1α." (PMID 35747796, 2022). "Unfortunately, therapeutic inhibition of TNFα in breast cancers have been particularly controversial, with several studies purporting concerns of increased breast cancer progression following TNFα treatment and competing studies indicating a lack of association with breast cancer recurrence." (PMID 35614362, 2022). "Furthermore, ST18 plays a variety of other roles, such as inhibiting breast cancer cells, regulating TNFα, inducing pancreatic β-cell apoptosis, and impairing insulin secretion; however, many of its biological functions have not yet been determined." (PMID 35783123, 2022). "Moreover, studies have shown that overexpressed OPG binds to and inhibits the activity of Apo2L/TRAIL, an apoptosis-inducing ligand of TNF, in vitro, which seems to help breast cancer cells survive, by escaping apoptosis." (PMID 36497209, 2022). "Moreover, PBP also induced the activation of the TNF-α/TNFR1 pathway in breast cancer cells, inhibited the expression of TNF-α in pigment melanoma cells, and triggered the production of ROS, thus inducing intracellular necroptosis." (PMID 36298031, 2022). "One epigenetically dysregulated lncRNA (LINC01983) and four lncRNA regulators (UCA1, RP11-221J22.2, RP11-221J22.1, and RP1-212P9.3) were identified to act as prognostic biomarkers of luminal breast cancer by controlling the TNF signaling pathway, Th17 cell differentiation, and T cell migration." (PMID 35954312, 2022). "Furthermore, the proinflammatory factors IL-1β, IL-8, and TNF-α, were highly expressed in breast cancer cells and tissues, and they were inhibited in MCF-7 breast cancer cells by downregulating the expression of ORM1." (PMID 35188865, 2022). "The differences between TNF-α and IL-19 at different stages of breast cancer." (PMID 35928364, 2022). "Likewise, GABARAP was upregulated in tumor necrosis factor-α-resistant breast cancer cells, concomitant with several other autophagy-related genes." (PMID 36430876, 2022). "A study of engineered Michigan cancer foundation-7 (MCF-7) breast carcinoma cell lines used to generate xenograft mouse models showed that TNF-α could prevent the MDR1 gene response against cytotoxic agents." (PMID 35814435, 2022). "In addition, studies have found that as the symptoms of breast cancer patients improve, serum TNF-α levels also decrease." (PMID 35783155, 2022). "Moreover, deferoxamine-induced increase of the intracellular iron can activate TGFβ and TNFα-dependent NF-κB signaling in highly aggressive breast cancer cells." (PMID 35845961, 2022). "Overall, TNFα is an important angiogenic target to be considered in breast cancer progression to attenuate any angiogenic response in the tumor environment that could lead to secondary organ metastasis." (PMID 36290384, 2022). "It has been reported that TNFα can induce EMT in breast cancer cells." (PMID 36290384, 2022).
breast carcinoma (continued). "Our findings suggest that a combination of SM-164 with systemic administration of TNFα or LPS could be an effective therapy for advanced breast cancers including those with metastases." (PMID 36119107, 2022). "Since merged expression of TNF signaling components was shown to be the most enriched in TNBC breast cancer cell lines, TNBC was used as the cell model for this Migration and invasion are two key phenotypes that are induced by TNF‐α and linked to cancer recurrence." (PMID 34197030, 2022). "In addition, propranolol exhibits adjuvant activity in the breast cancer vaccine model by modulating cytokines and TNF-α." (PMID 35893792, 2022). "However, TNFα upregulates mTOR activity in an NF-κB-dependent manner and inhibits autophagy in the human breast cancer MCF7 cell line." (PMID 35159248, 2022). "Interestingly, tumor necrosis factor (TNF)-mediated apoptosis is converted into pyroptosis with the expression of gasdermin C (GSDMC) mediated by programmed cell death ligand 1 (PD-L1) in breast cancer." (PMID 36209102, 2022). "Inhibition expression of TNF-α contributed to the therapy of breast cancer." (PMID 35136382, 2022). "Then, further studies confirmed that 17βE2 and TNFα could promote the expression of SVEP1 by activating the promoter of SVEP1 in breast cancer cells." (PMID 36699464, 2022). "When 93 breast carcinoma samples were analyzed, 97% of samples were positive for TNF-α." (PMID 36140220, 2022). "However, BV6 combination with TRAIL and TNFα strongly inhibited the growth and survival of both breast cancer cell lines." (PMID 36358282, 2022). "Additionally, the combined therapy of calcitriol and TNF−α had a greater cell growth inhibitory effect when compared to monotherapies in breast cancer cells." (PMID 36145297, 2022). "In breast cancer, G9a ablation induces TNF and necroptosis, thereby suppressing cancer relapse." (PMID 35455671, 2022). "Additionally, it was found that the TNF-α expression is a key parameter in the metastatic behaviour of breast cancer." (PMID 35928364, 2022). "Additionally, CM and its EXOs inhibited IL6, TNFα, and NFκB expression in spleens of immunocompromised rats and mammary tumor tissues." (PMID 36363614, 2022). "BHLHE41 expression suppresses apoptosis induced by TNFα in breast cancer cells, TWIST1 expression and migration in human endometrial cancer cells, is also associated with better prognosis of patients with breast cancer with HIF1 protein suppression." (PMID 34768959, 2021). "The TNF-α has antitumor activity in various tumor cell lines, including breast cancer cell lines." (PMID 35392343, 2021). "TNFα exhibits antitumor effects through activation of programmed cell death and migration and invasion of breast cancer cells through activation NF-κB-dependent EMT-inducing transcription factors (EMT-TFs) such as Twist1, Snail, Slug, and Zeb1/2 that drive inactivation of E-cadherin." (PMID 34220337, 2021). "A recent study demonstrated higher levels of circulating TNF-α in patients with breast cancer." (PMID 33986746, 2021). "That elevated PrPC may confer resistance to anticancer agents was soon confirmed by the demonstration of a causal relationship between increased PrPC expression and resistance to tumour necrosis factor-α (TNFα) in the MCF7 breast cancer cell line." (PMID 34638517, 2021). "Previous studies have confirmed that TNF-α promotes the progression and metastasis of many cancer types including hepatic carcinoma, hypopharyngeal cancer, colorectal cancer, and breast cancer." (PMID 33730072, 2021). "The ability of CN ethanol extract to suppress TNF-α may help to ameliorate the inflamed interaction between breast cancer cells, MDA-MB-231 and macrophage, THP-1." (PMID 34379689, 2021). "Our results suggest that a loss-of-function of AWP1 alters the TNF-α response of non-aggressive breast cancer cells by potentiating ROS-dependent NF-κB activation." (PMID 33816268, 2021).